IVL (involucrin)
Diseases named in the same sentence as IVL in open-access papers (continued):
Sharing a sentence is not in itself a finding about the gene and the disease.
tumor (39 papers, 1997 to 2026). "Oncogene expression in the K14/K5+ stem cell population led to rapid tumour development, whereas IVL+ committed progenitors remained resistant to transformation." (PMID 41507151, 2026). "In contrast, despite BRAFV600E-driven activation of MAPK signalling reaching similar levels in the progenitor population (IVL+), tumours exhibited a longer onset latency (125 days to tumour onset) and grew slowly." (PMID 41507151, 2026). "The resulting IVL+ derived tumours shared most histological features and a core transcriptional transformation programme with those originating from a K14/K5+ stem cell population." (PMID 41507151, 2026). "Assessment of the autophagy marker proteins combined with proteins from the epidermal differentiation cluster (involucrin and filaggrin) is often used for the evaluation of the differentiation status of normal and tumor cells." (PMID 34834228, 2021). "IVL (involucrin) was the most downregulated gene in the 3D model and was found to be downregulated in most of the tumor samples." (PMID 34283070, 2021). "Both TINCR and epithelial differentiation-associated genes, including IVL and KRT4, were significantly upregulated during OSCC cell calcium-induced differentiation but were reduced when cell dedifferentiation occurred in tumor spheres." (PMID 33732637, 2021). "Major components of the tumor microenvironment such as capillaries, human extracellular matrix, a stratified epidermis (involucrin, filaggrin) and basement membrane (laminin 332) are recapitulated in vitro." (PMID 30181613, 2018). "Collectively, these results thus indicated that administration of the ALDH inhibitor dyclonine sensitizes the involucrin+ differentiated tumor cells to sulfasalazine treatment in vivo." (PMID 30333913, 2018). "We recently showed that overexpression of Dsg2 under the control of the involucrin promoter in the skin of transgenic mice (Inv-Dsg2) resulted in hyperplasia of the epidermis and enhanced sensitivity to tumor induction." (PMID 25785582, 2015). "The overexpression of S100A7 significantly promoted tumor growth and decreased the expression of cytokeratin-1, TG-1, and involucrin in A-431 xenografts compared with the control animals." (PMID 26053695, 2015). "Sequentially, upregulation of involucrin and loricrin, which indicate terminal differentiation, strongly contributed to tumour growth inhibition along with partial apoptosis." (PMID 24260446, 2013). "Poorly differentiated tumours express very little involucrin even in the areas of extensive pimonidazole binding." (PMID 14760391, 2004). "Loss of membranous E-cadherin expression was more extensive in poorly differentiated carcinomas while, in individual carcinomas, membranous E-cadherin expression was stronger in those parts of the neoplasm that expressed the differentiation marker involucrin." (PMID 9166940, 1997). "Moreover we also treated non-tumour-bearing mice carrying one copy of the HRASG12V in the K14+ or IVL+ populations at 180 ± 5 days post-oncogene induction with the BRAFi." (PMID 41507151, 2026). "Interestingly, tumour samples found to express high levels of involucrin were also shown to express Brk." (PMID 37445934, 2023). "These tumours also displayed high expression levels of epidermal differentiation genes (such as IVL, LOR and KRT1), indicating that these tumours had undergone squamous metaplasia, and an activation of the WNT/β-catenin signalling pathway (expression of WNT10B and LEF1)." (PMID 34916592, 2022). "To investigate whether PULC treatment could alter the skin moisturizing response, we assessed the effect of PULC1 on protein levels of filaggrin and involucrin in dorsal skin lesions of the DNCB-treated NC/Nga mice." (PMID 30691219, 2019). "This raises the question of whether involucrin is an oxygen-regulated protein and, if so, whether it could serve as an endogenous marker for tumour hypoxia." (PMID 14760391, 2004).
tumor (continued). "Endogenous ORPs appear to be useful as hypoxia markers in normal tissues, but without a good understanding of the factors that control ORP expression, heterogeneity of expression of proteins such as involucrin will limit their scope as markers of human tumour hypoxia." (PMID 14760391, 2004). "All 46 tumour samples assessed were initially positive for involucrin expression; however, when we subtracted the median expression level of the normal samples, 36 out of the 46 (78%) tumour samples analysed expressed elevated levels of involucrin compared to normal tissues." (PMID 37445934, 2023). "Similar results were obtained in HRAS-driven tumours, where SOX2 expression was only seen in those arising from the IVL+ population." (PMID 41507151, 2026). "We performed immunohistochemical (IHC) analysis within tumor heterotransplants derived from UROtsa As_I cells to get a better understanding of protein localization in vivo for SOX2, IVL, and GRHL1." (PMID 37298099, 2023). "These tumours also showed high levels of KRT1 and IVL expression, indicating squamous differentiation." (PMID 34916592, 2022). "Five of the proteins (involucrin, CLCA4, S100A14, Serpin B5 and myosin-11) were found in the Pap test fluid; four of these proteins were also found in either the swab or tumor samples." (PMID 33413078, 2021). "FABP5, IVL, KRT6A, KRT15, KRT16, and TIMP2 expression profiles suggested relatively significant elevated expression in tumor tissues compared with the corresponding normal tissues." (PMID 32934956, 2020). "The expression of involucrin and LP34 demonstrates that, in all tumours, cells have reached the final program of differentiation, regardless of the grade." (PMID 32485997, 2020). "The strong staining of cystatin A, involucrin and SPRR3 was predominantly localized in the hyperkeratotic portion of tumor nests in well-differentiated ESCC tissues, but there was weak or negative staining in moderately- or poorly-differentiated ESCC tissues." (PMID 24796531, 2014). "This suggests that a differentiation-committed cell that has regained stemness potential, such as basal IVL+ or follicular LGR6+, could be the cell of origin in these tumours." (PMID 41507151, 2026). "The 17 tumour samples that expressed the highest levels of involucrin (ten-fold or more than the median level expressed by the normal samples), were all found to be positive for Brk mRNA expression." (PMID 37445934, 2023). "While there is no direct correlation between absolute levels of Brk and involucrin mRNA expression, it would appear that Brk is expressed in higher-grade involucrin-positive tumours." (PMID 37445934, 2023). "At last, FIDAS-5 treatment resulted in the occurrence of tumor cells with keratinization phenotype and involucrin expression in Xeno-76, but not in MTAP-WT C666-1 tumors." (PMID 34234122, 2021). "In contrast, treatment with cetuximab did not suppress tumor growth or affect involucrin expression in TE-8 (mesenchymal-like ESCC cells)-derived xenograft tumors." (PMID 28764725, 2017). "To test whether this influences tumour formation, we chemically induced tumours in EPI−/− mice, which lack three barrier proteins—Envoplakin, Periplakin, and Involucrin." (PMID 24843010, 2014). "The tumours did not have the histological appearance of trichofolliculomas and were negative for terminal differentiation markers of all three epidermal lineages: several hair keratins (HF), involucrin (IFE) and Oil Red (SG) (data not shown)." (PMID 18213391, 2008). "It is important to emphasise, however, that involucrin is an early marker for terminal differentiation so that tumour hypoxia, while not totally inhibiting differentiation, might arrest it at some point short of end stage differentiation." (PMID 14760391, 2004). "However, it does not explain why immunostaining for involucrin more closely matches pimonidazole binding in moderately differentiated tumours where the extent of immunostaining differs by a factor of only ca 1.5." (PMID 14760391, 2004).
tumor (continued). "If involucrin were also induced in the range of 6–20 mmHg, it might be expressed in tumour microregions that did not bind detectable levels of pimonidazole." (PMID 14760391, 2004). "Interestingly, no significant change was observed in the levels of involucrin upon either K5 or K14 overexpression alone, indicating that perhaps both are required for conferring a more de-differentiated phenotype to the tumor cell." (PMID 28225793, 2017).
cancer (22 papers, 1997 to 2024). A tumor composed of atypical neoplastic, often pleomorphic cells that invade other tissues. "The heat map shows positive correlation between GJB2 and the five genes (GJB6, KRT6A, KRT6B, KRT14, and IVL) in pan-cancer." (PMID 37427102, 2023). "When PLR327F-LD41 cells were cultured in a mixture of Matrigel and collagen I, they generated 3D colonies (designated cancer organoids, or COs) with involucrin (IVL)-positive keratinizing cells in the center (IVLinner COs)." (PMID 34934075, 2021). "In this study, 4HR accelerated carcinoma epithelial cell differentiation showing upregulation of involucrin and keratins expression." (PMID 34333710, 2021). "Coexpression of keratin 14, a basal cell marker of squamous and glandular epithelia, keratin 5 and involucrin are reported to represent a stem cell or progenitor cell phenotype in cancer cells." (PMID 26807202, 2015). "Involucrin immunoreaction was observed in all but one poorly differentiated carcinoma." (PMID 32485997, 2020). "Squamoid features and involucrin expression, detected in 22% and 27% of cases respectively, correlated with each other and were associated with high-grade atypia, a solid-nest pattern, cancer cell necrosis on histology and negative oestrogen receptor status." (PMID 9166948, 1997). "There was also a positive correlation between high EDAR and expression of the skin-specific genes LORICRIN (LOR), KERATIN1 (KRT1) and INVOLUCRIN (IVL), suggesting the occurrence of squamous metaplasia within the EDAR-high cancers." (PMID 34916592, 2022). "cystatin A, involucrin and SPRR3 expression was significantly higher in carcinoma with well differentiation than that with moderate or poor differentiation (P = 0.002, P = 0.003 and P = 0.010, respectively)." (PMID 24796531, 2014). "In opposite, HN-CICs after Sh-GRP78 lentiviruses infection displayed decreased expression of "cancer stemness" genes (Oct-4, Nanog, and Nestin) but enhanced expression of epithelial differentiation marker, CK18 and Involucrin." (PMID 20979610, 2010). "When cultured under 3-D at ALI system, the expression of both early and late differentiation markers involucrin and filaggrin, as well as viral late gene L1, were detected in the cornified layer of VIN-ALI, suggesting different HPV genomic status from cancer cells." (PMID 37376685, 2023). "When cultured under a 3-D ALI system, the expression of both early and late differentiation markers involucrin and filaggrin, as well as viral late gene L1, were detected in the cornified layer of VIN-ALI 3-D culture derived, suggesting quite a different HPV genomic status from cancer cells." (PMID 37376685, 2023). "In addition, the involucrin-positive cells showed a strong tendency to be CD271− and vice versa, and this mutually exclusive expression was evident in the normal, dysplastic, and carcinoma tissues." (PMID 27469492, 2016).
skin disorder (6 papers, 2013 to 2026). Any deviation from the normal structure or function of the skin or subcutaneous tissue that is manifested by a characteristic set of symptoms and signs. "Premature, enhanced expression of IVL occurs in some skin disorders linked to an imbalance in the keratinization process." (PMID 39157429, 2024). "The treatment also enhanced the expression of skin barrier proteins, including filaggrin and involucrin, and reduced serum IgE levels and T helper 2-associated cytokines, indicating its potential as a functional food for managing pollution-induced skin disorders." (PMID 39857357, 2024). "A rise in abundance of involucrin is reported to result in compromised epidermal permeability barrier eventually leading to increased prevalence of certain cutaneous disorders." (PMID 39819313, 2025).
infection (5 papers, 2010 to 2022). The state of being infected such as from the introduction of a foreign agent such as serum, vaccine, antigenic substance or organism. "At 72 h after infection, increased RORα4 expression significantly induced the expression of early and intermediate differentiation markers (keratin 1/10 and involucrin), as well as granular layer markers (loricrin and filaggrin) at both mRNA and protein levels." (PMID 23922987, 2013). "The ex vivo infection model showed that the barrier gene FLG and IVL were generally inhibited in S. aureus infection model." (PMID 33828484, 2021). "In non-infection model, IFN-λ1 100 ng/ml increased IVL mRNA expression." (PMID 33828484, 2021).
adenocarcinoma (1 paper, 2009). A common cancer characterized by the presence of malignant glandular cells. "IVL (involucrin), which we found up-regulated in adenocarcinoma and encodes a protein of the terminally differentiated keratinocyte." (PMID 19812696, 2009).
benign tumours (1 paper, 2014). "Thus combined deletion of envoplakin, periplakin, and involucrin decreased epidermal susceptibility to chemically induced benign tumours." (PMID 24843010, 2014).
IVL also shares sentences with these, for which no sentence is quoted: metastatic melanoma (4 papers); actinic keratosis (1); adenosquamous carcinoma (1); Airway obstruction (1); ameloblastoma (1); basal cell tumours (1); cervical intraepithelial neoplasia (1); childhood onset asthma (1); cutaneous melanoma (1); cutaneous squamous cell carcinoma (1); Erythema (1); glioblastoma (1); keratoacanthoma (1); lung adenocarcinoma (1); lymph node metastasis (1); melanocytic nevus (1); metastatic cancer (1); odontogenic cyst (1); pancreatic cancer (1); skin changes (1); thyroid (1).